ZNF816-ZNF321P (ZNF816-ZNF321P readthrough)
Synonyms: ZNF816-ZNF321
Gene: Protein-coding gene on chromosome 19 (52,928,475 to 52,962,823, reverse strand). Ensembl gene ENSG00000221874.
Genetic constraint (gnomAD): Loss-of-function variants: 8 observed, 8.86 expected, observed/expected ratio (o/e) 0.9, 90% interval 0.53 to 1.6. That is too few expected variants to judge how well the gene tolerates losing a copy. Missense variants: 282 observed, 289.22 expected, observed/expected ratio (o/e) 0.98, 90% interval 0.88 to 1.08. Synonymous variants: 96 observed, 96.31 expected, observed/expected ratio (o/e) 1, 90% interval 0.84 to 1.18.